HIF1A (hypoxia inducible factor 1 subunit alpha)
Diseases named in the same sentence as HIF1A in open-access papers (continued):
Sharing a sentence is not in itself a finding about the gene and the disease.
tumor (continued). "The number of perfused vessel was higher in HIF-1α-KD tumors irrespective of hypoxic and nonhypoxic tumor regions." (PMID 33142239, 2020). "During tumor progression, tumor metabolism is regulated by a number of metabolic regulators, including HIF-1α, AMPK, mTOR, and PPAR gamma coactivator 1 alpha (PGC-1α), wherein AMPK indirectly regulates the stability of HIF-1α through metabolites." (PMID 33109235, 2020). "While it has be shown that GATA3 is required for the stabilization of a hypoxic microenvironment through binding with HIF1-α, this current study shows the possible role of GATA 2 and GATA3 in altering the glycosylation of tumor glycoproteins, thereby potentially contributing to cell invasiveness." (PMID 32850359, 2020). "Furthermore, oxidative stress in tumor cells induces the activation of pro-autophagy factors, such as LC3, BNIP3L, ATG16L, BNIP3, NF-κB, and HIF-1α, which promote the degradation of caveolin-1 (Cav-1), leading to autophagy activation." (PMID 32707662, 2020). "The expression of several growth factors that regulate tumor growth after hypoxia injury, such as insulin-like growth factor (IGF2), transforming growth factor (TGF), and platelet-derived growth factor (PDGF), are under HIF-1α regulation." (PMID 32751958, 2020). "HIF1α stabilized by LSD1 cooperates with CBP and MTA1 to enhance VEGFA-induced tumor angiogenesis." (PMID 32070413, 2020). "Patients with high expression of both HIF-1α and SP1 were more likely to have tumor metastasis." (PMID 31892989, 2020). "STIM1 and HIF-1α protein levels were also upregulated in some PDAC tumor samples compared to non-tumor samples." (PMID 33178018, 2020). "18F-FDG-uptake, high HIF-1A/GLUT1/EMT and cold tumour immune status in patients with OSCC." (PMID 32238919, 2020). "NPs/ENPs plus PDT-treated tumor tissues displayed enhanced HIF-1α expression, compared with the non-PDT-treated group, indicating that PDT aggravated intracellular hypoxia." (PMID 33240803, 2020). "The apoptosis induced by MEG3 was also accompanied by SUC accumulation, indicating a mechanism of tumour suppression by MEG3 might be through SUC accumulation, HIF‐1α activation and apoptosis promotion during the malignant transformation from OLP to OSCC." (PMID 31793175, 2020). "HIF-1α protein stability is dependent on VHL, a tumor suppressor gene that downregulates HIF-1α." (PMID 32707933, 2020). "For example, hypoxia or overexpression of HIF-1α promotes EMT through the regulation of TWIST expression by directly binding to the hypoxia-response element in the TWIST proximal promoter, which leads to tumor progression and metastasis." (PMID 33374849, 2020). "Taken together, relying only on ‘proliferation’ data in vitro and in vivo with the currently available pre-clinical models is not adequate to determine the comprehensive tumor suppressive/promoting effects of HIF1α (or HIF-VHL pathway) in human cancer." (PMID 33077781, 2020). "Notably, TCGA data showed higher HIF1A and TGFB1 gene expression in HCC tissues and its correlation with the overall survival rate, tumor cell proliferation and EMT." (PMID 31819036, 2019). "Indeed, activation of the PI3K/AKT pathway in both tumor and endothelial cells increases VEGF secretion by both HIF-1α-dependent and HIF-1α-independent mechanisms." (PMID 31711427, 2019). "Moreover, we examined the transcription levels in harvested tumor xenograft samples, and results showed that the mRNA levels of HIF1α and ATG5 were notably upregulated in HIF1α-overexpressed group." (PMID 31700698, 2019). "For instance, HIF1α in tumor cells upregulates the expression of CD73, which is located on the surface of many tumor cells and which is responsible for the conversion of adenosine monophosphate to adenosine resulting in increased adenosine concentrations in TME." (PMID 31849941, 2019).
tumor (continued). "Regardless of its abundance in the VHL tumor, a dysfunctional HIF1α was consistent with the oncocytic phenotype and its benign nature." (PMID 30728892, 2019). "HIF-1α expression under these conditions established a pro-angiogenic macrophage phenotype, indicating that S1P/S1PR1 signaling may promote tumor angiogenesis in general." (PMID 31379883, 2019). "In different sets of tumor cell lines, SCF was found to be induced by either HIF1α or HIF2α." (PMID 30781787, 2019). "Thus, we further explored the effect of Bclaf1 on HIF-1α transcription and protein levels and the biological significance of Bclaf1 in HCC angiogenesis and tumor progression under hypoxic conditions." (PMID 30367150, 2019). "We found that the tumor grade, stage, size, vascular invasion, and necrosis were also associated with a high HIF Pathway score, but not with HIF-1α alone." (PMID 30943919, 2019). "HIF1a expression was not related to LBD or tumour prominence in a univariate regression analysis (p = 0.21 and p = 0.67, respectively)." (PMID 31323773, 2019). "HIF-1α is an important transcription factor that regulates the cellular response to hypoxia, and high levels of HIF-1α expression promote angiogenesis, cell proliferation, cell survival, and tumor progression." (PMID 30177838, 2019). "Furthermore, increased HIF-1α expression also correlated with tumor size, TNM staging, and depth of tumor invasion." (PMID 31673244, 2019). "Further studies in this area will be important to assess whether other signaling pathway (e.g., HIF-1α, is also known to induce CD7338,40) does lead to any functional response involving interaction with 4-1BB ligation to boost anti-tumor T cell activity." (PMID 30635578, 2019). "In a study looking at mouse models of breast, colon, and liver tumors, knockout of HIF-1α and HIF-2α decreased tumor growth, but only HIF-2α knockout lead to decreased expression of macrophage colony-stimulating factor receptor (M-CSFR) and CXCR4 on tumor-infiltrating macrophages." (PMID 30931508, 2019). "A previous study demonstrated that TS expression was significantly correlated with glucose transporter 1 (Glut1) and hypoxia-inducible factor-1α (HIF-1α), key elements for determining the amount of FDG uptake within tumor cells, in patients with primary lung cancer." (PMID 31434972, 2019). "There is a controversy whether these proteins act as oncogenes or suppressor genes in tumors, although there are literature data about a tumor-suppressive function of SIRT-3 and an oncogenic role of HIF-1α and p-mTOR in HCC." (PMID 30917505, 2019). "Accordingly, silencing of endothelial PAS domain protein 1 (EPAS1; best known as HIF2A) in clear cell renal cell carcinoma or HIF1A in melanoma and prostate cells reduced PD-L1 expression and restored cytotoxic T lymphocyte (CTL)-mediated tumor cell killing in vitro." (PMID 31535086, 2019). "Furthermore, in GBM, signaling through HIF1α and AHR can crossregulate each other at several points of contact, coordinating metabolic regulation of anti-tumor immunity as well as tumor growth." (PMID 31866995, 2019). "As a tumor is often described as being like a “chronic wound”, the hypoxic conditions and high concentration of cytokines and growth factors IL-1α, IL-1β, IL-6, FGF-2, IGF-1, TGF-β, VEGF-A, HIF-1α, EGF, TGF-α are a likely trigger for MSCs recruitment to tumor microenvironments." (PMID 31569731, 2019). "We monitored for effect of handling and storage, and noted that the HIF-1α protein content of both tumor and normal tissues did not vary over time (R2 = 0.0038 and 0.0152, respectively) which ranged from 2 to 14 years at -80 °C." (PMID 30943919, 2019). "Besides, by inactivating HIF-1α, SIRT1 represses HIF-1 target genes and adversely effects tumor growth and angiogenesis." (PMID 31687086, 2019). "Conversely, lack of HIF-1α in myeloid cells slows tumor progression, indicating enhanced anti-tumor immunity." (PMID 29953680, 2019).
tumor (continued). "We note that HIF‐1A may act as a converging point to mechanically regulate the adaptive response of PDAC to hypoxia and the overall architecture of the tumor microenvironment." (PMID 30538116, 2019). "On the other hand, inhibitions of PI3K/AKT and HIF1A simultaneously (TC6) was necessary to suppress the LGG-II tumor cells, but not the LGG-I and Grade-IV cells in the tumorigenic niche." (PMID 31263189, 2019). "In addition, under hypoxic stimulation, HT1080 cells can generate pro-angiogenic factor, including HIF-1α, VEGF and MMPs to promote tumor angiogenesis, and is an ideal model for studying tumor invasion and metastasis." (PMID 31022939, 2019). "We evaluated how the expression of HIF1a and VHL relates to clinical and genetic factors in UM and established that genetics, but not tumour size, are strongly associated with the level of these markers." (PMID 31323773, 2019). "Tumor-derived exosomes can promote the initiation and progression of metastasis by targeting EMT-related factors, such as transforming growth factor beta (TGFβ), caveolin-1, hypoxia-inducible factor 1 alpha (HIF-1α), and β-catenin." (PMID 30925925, 2019). "In addition, HOTAIR knockdown significantly suppresses tumor growth and ki-67 expression, increases miR-217 levels and decreases the expression of HIF-1α and AXL, inhibiting tumor growth and EMT." (PMID 31072041, 2019). "Our previous results showed that low-dose irinotecan results in a lack of tumor vascularization and inhibition of HIF-1α protein accumulation, leading to impaired adaptation of tumor cells to their environment." (PMID 31627299, 2019). "The combination of an HIF-1α inhibitor (2-mercaptoethanol,2-ME) and ROS inducer (arsenous oxide, As2O3) can prohibit proliferation and migration and promote apoptosis in MG63 cells in vitro while inhibiting tumour growth in vivo." (PMID 31905813, 2019). "Thus, overexpression of HIF-1α under hypoxic conditions accelerates lactic acid production by promoting glycolysis and suppressing the TCA cycle, leading to an acidic tumor microenvironment." (PMID 30845711, 2019). "Moreover, by using tumour tissue samples from CRC patients, we certified that the miRNA‐148a level is inversely related to the expression of HIF‐1α and VEGF." (PMID 30834693, 2019). "In two independent cohorts, we showed that the high expression of CAIX and HIF-1α is of prognostic significance and the best prognosis for OSCC patients in an earlier study of our group was actually found for low HIF1a ⁄CAIX protein expressing tumor patients." (PMID 30654595, 2019). "This IL-6-dependent metabolic shift is absent in DU145 cells, where the Warburg effect is probably maintained through the HIF-1α/PKM2/STAT3 axis, further confirming the distinctive response to the inflammatory cytokine of these two differently staged tumor cell lines." (PMID 31500219, 2019). "In addition, a complex can be formed between the PKM2/P300/PHD3/HIF-1α/HIF-1β in the nucleus, and finally regulate the tumor fine glucose metabolism, O2 consumption and CO2 production." (PMID 31391918, 2019). "More specifically, it has been observed that hypoxia and enhanced HIF‐1α and HIF‐2α expression and activity, which frequently occur during tumour progression, may result in the upregulation of different stemness gene products that increase tumourigenicity." (PMID 30959553, 2019). "Hypoxic conditions downregulated MICA on the surface of tumor cells by different mechanisms, including shedding of this NKG2DL mediated by HIF1α-dependent upregulation of the matrix metalloproteinase A disintegrin and metalloproteinase domain-containing protein 10 (ADAM10)." (PMID 31535086, 2019). "Likewise, enhanced HIF-1α expression correlated with tumor size (P = 0.049), TNM staging (P = 0.014) and depth of tumor invasion (P = 0.004)." (PMID 31673244, 2019).
tumor (continued). "It is noteworthy that expression levels of VegfA and Hif1a are higher in metastatic lymph nodes of WT and Stat4−/− mice compared to primary tumors and non-metastatic lymph nodes of tumor bearing mice." (PMID 32010142, 2019). "In a multivariate model with the addition of either chromosome 3 or BAP1 status, tumour size also did not relate significantly to HIF1a expression." (PMID 31323773, 2019). "It has been reported that hypoxia, particularly HIF-1α, may promote the expression of CXCR4 and activate the SDF-1α/CXCR4 signaling axis, contributing to tumor cell invasion and metastasis." (PMID 31336612, 2019). "Tumor size >2 cm (P = .033), histological grade III (P = .012), lymph node-positive (P = .024), TNM stage III (P = .005), HIF-1α-positive expression (P < .001), and c-myc-positive expression (P = .003) were the risk factors of postoperative survival in TNBC patients." (PMID 31577739, 2019). "Depletion of B cells via anti-CD20 antibody in the HIF-1α knockout PDA model allowed T cell infiltration into the tumor, but did not change Treg percentage." (PMID 30931508, 2019). "We have explored the status of HIF-1α and EGFR in a unique cohort of CBC-patients that, to our knowledge, is the largest of its kind with access to detailed patient-information and a long follow-up period along with tumor-tissue samples." (PMID 31821370, 2019). "To determine whether cardamonin inhibited the HIF-1α pathway in vivo, we assessed HIF-1α protein levels and its downstream targets in tumor tissues." (PMID 31455352, 2019). "In response to hypoxia, tumor tissues produce and secrete high levels of several pro- angiogenenic factors such as VEGF-A, which transcription is under the control of the hypoxia- inducible factor HIF-1α." (PMID 31448053, 2019). "Likewise, HIF-1α subunit, is negatively regulated by the VHL tumor suppressor and miR-155 has been shown to downregulate the expression of VHL tumor suppressor, a protein involved in the cellular response to hypoxia." (PMID 30842790, 2019). "As HIF-1α is another transcriptional activator of TG2, by mediating the depletion of VHL, TG2 can favor the expression of itself in RCC cells thence act as a tumor-promoter." (PMID 30736384, 2019). "Similarly, administration of fucoidan also inhibits HIF-1α and VEGF expression in female athymic nude mice, BALB/c injected with T24 cells in vivo, accompanied by a reduction of tumor growth." (PMID 31041568, 2019). "To understand how TNuF or the combined treatment negatively regulates neoplastic processes and angiogenesis, we set out to examine possible pathways that regulate productions of epidermal growth factor receptor (EGFR), vascular endothelial growth factor (VEGF), HIF-1α and CD31 in tumor tissues." (PMID 31426614, 2019). "During tumour progression, VEGF-B and VHL decrease, while HIF1a increases." (PMID 31337000, 2019). "The hypoxic tumor microenvironment in high-grade tumors, as measured by significantly decreased HP 13C-urea perfusion and increased PIM staining, played a key role in increasing lactate production through increased Hif1α and then Ldha expression." (PMID 30813322, 2019). "HIF-1α and LAPTM4B expression was correlated with tumor stage (p < 0.05)." (PMID 30746305, 2019). "Although the activation of autophagy by hypoxia in tumor cells can occur either in a HIF-1- dependent or HIF-1-independent manner, the major negative impact of hypoxia-induced autophagy on the anti-tumor immunity involves HIF-1α." (PMID 31540045, 2019). "Our study indicated that tumor angiogenesis was inhibited by antagonizing CXCR4, although this anti-angiogenesis approach could result in tumor hypoxia inducing HIF-1α." (PMID 31336612, 2019). "After HIF-1α is activated and combining to the hypoxia responsive elements in the 5′-terminal enhancer region of VEGF, the transcription of VEGF is initiated, and the expression is increased, thereby, the tumor angiogenesis is promoted." (PMID 31531063, 2019).
tumor (continued). "We suggest that HIF-1α may act as a converging point to mechanically regulate the adaptive response of HCC to hypoxia and the overall architecture of the tumour microenvironment." (PMID 30575816, 2019). "In support of this idea, DAOY-NERT2HIF2α−/− cells exhibited higher HIF1α protein levels under hypoxic conditions and treatment of the DAOY-NERT2HIF2α−/− cells with the HIF1α inhibitor KC7F2 reduced tumor growth both under control and Notch1 ICD-activated conditions." (PMID 29993038, 2018). "Elevated HIF-1α levels were observed in different human cancer types and correlate with increased tumor aggressiveness, invasiveness and often with negative overall survival rates and poor prognosis." (PMID 30563292, 2018). "Several tumor-promoting genes such as CXCR4, LSH, MMP9, and hypoxia-inducible factor (HIF)-1α are thought to contribute to radioresistance, and their elevated expression is consistent with their proposed role in cancer progression, metastasis, and radiotherapy." (PMID 29706625, 2018). "But in tumor, a lot of TAMs were CD163 and HIF1α-positive, and less expressed HLA-DR and C9." (PMID 29900010, 2018). "In addition, a previous study showed that HIF-1α upregulates NDUFA4L2 expression during hypoxia in mouse embryonic fibroblasts (MEFs) and tumour cells." (PMID 29967776, 2018). "We were disappointed that there is no alterations in cell proliferation and expression of tumor progression-related genes including HIF1A, TGFβ1 and VEGF at RNA levels but decrease of trans-well cell migration assays in HCC cells PLC5, SNU449 and Huh7." (PMID 29568350, 2018). "In contrast to other clinically used microtubule inhibitors, MPT0B098 is effective in suppressing tumor growth despite p-gp170/MDR status, and can destabilize HIF-1α mRNA under hypoxic conditions by inhibiting the translocation of human antigen R (HuR) from the nucleus to the cytoplasm." (PMID 29592811, 2018). "Since HIF-1α is a reliable indicator of the degree of tumor hypoxia, the high expression of HIF-1α in cells with hypoxia culturing indicated a successful simulating of tumor hypoxia microenvironment." (PMID 29461122, 2018). "As revealed by T2-weighted magnetic resonance imaging and immunohistochemical analysis, the intratumoral hypoxia was greatly alleviated, and the level of hypoxia inducible factor-1α (HIF-1α) and vascular endothelial growth factor (VEGF) in tumor was obviously down-regulated." (PMID 29461122, 2018). "In agreement, our results also showed that pharmacological inhibitors targeting the IFN-α signaling and pathways could not only modulate HIF-1α expression but also tumorigenic activities such as EMT and tumor invasion." (PMID 29587825, 2018). "On the basis of these studies, we propose that a functional network between HIF-1α, GPER and Notch may integrate tumor microenvironmental cues to induce robust EMT in cancer cells." (PMID 29996493, 2018). "We measured ascorbate, HIF-1α, and HIF-2α protein and HIF downstream targets BNIP3, CA9, cyclin D1, GLUT1, and VEGF (combined to generate the HIF pathway score) in VHL-defective ccRCC (n = 73) and VHL-proficient pRCC human tumor tissue (n = 41)." (PMID 30555801, 2018). "Moreover, both HIF1α and OATP3A1 were strongly expressed in PDX tumor samples and their original clinical liver tumor specimens." (PMID 29706843, 2018). "Other authors already suggested that HIF-1α is not important for tumor formation, but has a significant impact on sarcoma metastasis." (PMID 30513863, 2018). "HIF-1α- and HIF-2α-expressing macrophages have been shown to promote tumor progression." (PMID 29896451, 2018). "Trying to get inside to the mechanism responsible for the reduced tumour growth and reduced metastatic formation, we have found that reduced AQP1‐dependent neovessel formation is responsible for HIF‐1α increase, reduced expression of MMP2 and increased expression of caspase‐3." (PMID 29044946, 2018).